FKBP1A (FKBP prolyl isomerase 1A)
Description:
Keeps in an inactive conformation TGFBR1, the TGF-beta type I serine/threonine kinase receptor, preventing TGF-beta receptor activation in absence of ligand. Recruits SMAD7 to ACVR1B which prevents the association of SMAD2 and SMAD3 with the activin receptor complex, thereby blocking the activin signal. May modulate the RYR1 calcium channel activity. PPIases accelerate the folding of proteins. It catalyzes the cis-trans isomerization of proline imidic peptide bonds in oligopeptides.
Synonyms: FKBP-12; FKBP-1A; FKBP1; FKBP12; PKC12; PPIASE; FKBP12C; PKCI2
Tractability: Small molecule: an approved drug acts on it; a structure with a bound ligand is known; a high-quality ligand is known; it has a high-quality binding pocket; it belongs to a druggable protein family. Antibody: UniProt places it where antibodies can reach, with medium confidence. PROTAC: it is named in the literature on targeted protein degradation; ubiquitination databases record sites on it; its protein half-life has been measured; a small molecule that binds it is known.
Target class: Isomerase; Enzyme
Chemical probes: ASCOMYCIN, DTAGv-1 (high quality), TACROLIMUS (high quality), dTAG-13 (high quality)
Gene: Protein-coding gene on chromosome 20 (1,368,977 to 1,393,164, reverse strand). Ensembl gene ENSG00000088832.
Subcellular location: Cytoplasm, cytosol; Sarcoplasmic reticulum membrane
Subcellular location (Human Protein Atlas): Golgi apparatus; Basal body; Cytosol; Primary cilium
Pathways (Reactome):
Disease: Potential therapeutics for SARS; SARS-CoV-1 activates/modulates innate immune responses; TGFBR1 LBD Mutants in Cancer
Signal Transduction: TGF-beta receptor signaling activates SMADs; TGF-beta receptor signaling in EMT (epithelial to mesenchymal transition); mTORC1-mediated signalling
Immune System: Calcineurin activates NFAT
Gene Ontology:
Molecular function: activin receptor binding; calcium channel regulator activity; FK506 binding; I-SMAD binding; peptidyl-prolyl cis-trans isomerase activity; protein binding; signaling receptor inhibitor activity; type I transforming growth factor beta receptor binding; macrolide binding; transforming growth factor beta receptor binding; transmembrane transporter binding
Biological process: amyloid fibril formation; negative regulation of activin receptor signaling pathway; negative regulation of transforming growth factor beta receptor signaling pathway; positive regulation of canonical NF-kappaB signal transduction; regulation of amyloid precursor protein catabolic process; regulation of immune response; regulation of protein localization; regulation of skeletal muscle contraction by regulation of release of sequestered calcium ion; supramolecular fiber organization; 'de novo' protein folding; heart morphogenesis; heart trabecula formation; protein folding; protein maturation; protein refolding; regulation of cardiac muscle contraction by regulation of the release of sequestered calcium ion; T cell activation; ventricular cardiac muscle tissue morphogenesis
Cellular component: cytoplasm; cytosol; membrane; Z disc; cytoplasmic side of membrane; ryanodine receptor complex; sarcoplasmic reticulum; sarcoplasmic reticulum membrane; terminal cisterna
Genetic constraint (gnomAD): Loss-of-function variants: 5 observed, 9.12 expected, observed/expected ratio (o/e) 0.55, 90% interval 0.29 to 1.15. That is too few expected variants to judge how well the gene tolerates losing a copy. Missense variants: 50 observed, 113.95 expected, observed/expected ratio (o/e) 0.44, 90% interval 0.35 to 0.56. Synonymous variants: 40 observed, 44.02 expected, observed/expected ratio (o/e) 0.91, 90% interval 0.7 to 1.18.
Homologues: Orthologues: chimpanzee FKBP1A (100% identical), macaque FKBP1A (100% identical), guinea pig Fkbp1a (99% identical), mouse Fkbp1a (97% identical), rat Fkbp1a (91% identical), dog FKBP1A (84% identical), Drosophila melanogaster Fkbp12 (76% identical), Caenorhabditis elegans fkb-5 (44% identical), Caenorhabditis elegans fkb-4 (40% identical). Paralogues in human: FKBP1C (95% identical), FKBP1B (83% identical), FKBP10 (48% identical), FKBP4 (47% identical), FKBP5 (46% identical), FKBP9 (46% identical), FKBP2 (44% identical), FKBP3 (44% identical), FKBP11 (34% identical), FKBP15 (33% identical), FKBP14 (32% identical), FKBP7 (31% identical), and 6 more.
Diseases named in the same sentence as FKBP1A in open-access papers:
FKBP1A is named in the same sentence as 118 diseases in open-access papers, as found by Europe PMC text mining. Sharing a sentence is not in itself a finding about the gene and the disease. The quoted sentences say what the papers report.
breast carcinoma (14 papers, 2011 to 2025). "In contrast, downregulated FKBP1A in breast cancer tissues is associated with poor prognosis and increased resistance to chemotherapy." (PMID 38570626, 2024). "Recent studies showed that the expression of FKBP1A in breast cancer was decreased significantly, and low expression of FKBP1A was associated with poor prognosis and increased resistance to chemotherapy." (PMID 36361587, 2022). "While an aberration of TGF-beta type 1 receptor is associated with a significantly increased risk of breast cancer, FKBP1A may also be associated with an elevated risk of breast cancer, as our study indicated." (PMID 32497068, 2020). "During the processes of everolimus-inducing ferroptosis in breast cancer cells, an everolimus-related protein named FK506-binding protein 1A (FKBP1A) negatively regulates the SLC3A2 expression to promote anti-proliferation effect of Th9 lymphocytes." (PMID 38705513, 2024). "WB, Co-IP, cell proliferation assay, Edu staining, ROS and GSH assay and in vivo tumor xenograft assays were performed to verify FKBP1A/SLC3A2 axis in everolimus inducing ferroptosis of breast cancer." (PMID 37484811, 2023). "Multiple studies reported that FKBP1A was involved in tumorigenesis including head and neck squamous cell carcinoma, prostatic cancer cell line, lung adenocarcinoma and breast cancer." (PMID 36361587, 2022). "FKBP1A mediates the immunosuppressive and antitumor effects of rapamycin, widely used in the treatment of breast cancer." (PMID 32497068, 2020). "In addition, as FKBP1A degrades MDM2, it makes cells susceptible to chemotherapy-induced apoptosis; in breast cancer patients with high MDM2 expression, FKBP1A elevated sensitivity to anthracycline chemotherapeutic agents." (PMID 36499275, 2022). "Ten genes, including FKBP1A, were identified as biomarkers for breast cancer." (PMID 34691238, 2021).
prostate carcinoma (12 papers, 2013 to 2024). A carcinoma that arises from epithelial cells of the prostate gland. "It has been found that FKBP1A is up-regulated in prostate cancer and head and neck squamous cell carcinoma, and enhances paclitaxel-resistance and associates with lymph node metastasis." (PMID 38321024, 2024). "Simply put, SNHG15 was involved in the regulation of the miR-338-3p/FKBP1A axis, thus encouraging the malignancy and tumorigenesis of prostate cancer." (PMID 37056344, 2023). "For instance, the upregulation of SNHG15 in prostate cancer tissues resulted in a rapid progression of the disease by increasing the expression of FKBP1A via miR-338-3p absorption." (PMID 37056344, 2023). "Another LncRNA SNHG15 promoted prostate cancer progression by manipulating the miR-338-3p/FKBP1A axis." (PMID 36499275, 2022). "Meanwhile, the expression levels of FKBP1A mRNA were higher in bladder cancer, gastric cancer, head and neck cancer, kidney cancer, lymphoma, myeloma, ovarian cancer, prostate cancer and sarcoma compared to the normal tissues." (PMID 36361587, 2022). "FKBP1A has been shown to have a clear role in other cancers including prostate cancer and head and neck squamous cell carcinoma." (PMID 35719379, 2022). "Recently, miR-195-5p/FKBP1A was identified as a key factor for paclitaxel-resistant prostate cancer cells to paclitaxel via LncRNA AFAP1-AS binding to the 3ʹUTR of FKBP1A." (PMID 36361587, 2022). "lncRNA SNHG15 enhances EMT of prostate cancer by regulating miR-338-3p/FKBP1A axis." (PMID 34691238, 2021). "In prostate cancer, by sequestering miR-515-5p, Circ-PAPPA enhanced malignant phenotypes of prostate cancer cells by enhancing the expression of FKBP1A." (PMID 36499275, 2022). "FKBP1A can be regulated by SNHG15, which is closely related to the occurrence of prostate cancer." (PMID 37370041, 2023). "The silencing of LncRNA AFAP1-AS1 could reduce FKBP1A expression through miR-195-5p, thereby improving paclitaxel tolerance in PTX-resistant prostate cancer cells." (PMID 36499275, 2022).
Alzheimer disease (5 papers, 2016 to 2024). A progressive, neurodegenerative disease characterized by loss of function and death of nerve cells in several areas of the brain leading to loss of cognitive function such as memory and language. "Additional FKBPs have been put forward as potential drug targets in steroid hormone-associated cancer and psychotic disorders (FKBP4, 5, 8), and Alzheimer’s disease (FKBP1A, 4, 5)." (PMID 35456020, 2022).
hepatocellular carcinoma (5 papers, 2022 to 2024). A malignant tumor that arises from hepatocytes. "We constructed the prognostic risk score for patients with hepatocellular carcinoma as follows: risk score = (0.3519) × PPM1G + (0.0637) × FKBP1A + (0.0673) × STAM + (0.0373) × MAD2L2 + (0.0031) × TBL1XR1 + (0.0172) × ANXA5." (PMID 38049741, 2023). "Therefore, our findings suggest that it is feasible to use FKBP1A as a potential diagnostic and prognostic marker for hepatocellular carcinoma in clinical practice." (PMID 36361587, 2022). "Consistent with our results, a recent study revealed that protein expression of FKBP1A was found in hepatocellular carcinoma tissues and its expression was correlated with stage, grade, and metastasis of the tumor." (PMID 38570626, 2024).
astrocytomas (4 papers, 2011 to 2020). "FKBP12 or FKBP1A has been shown to inhibit TGFβ type 1 receptor, and its overexpression has been reported in astrocytoma." (PMID 21811619, 2011). "Given that FKBP1A is a component of the EGFR/FKBP1A/HIF-2α pathway, which plays a role in childhood high-grade astrocytomas, increased FKBP1B levels may also cause astrocytomas." (PMID 28394947, 2017). "FKBP1A has also been shown to inhibit TGF-beta type 1 receptor and it was found overexpressed in childhood astrocytomas, which presented as the EGFR/FKBP12/HIF-2alpha pathway." (PMID 32497068, 2020).
glioblastoma (4 papers, 2012 to 2024). The most malignant astrocytic tumor (WHO grade IV). "Despite preceding research suggesting the anticancer effect of FKBP1A, the role of FKBP1A in glioblastoma and the underlying biologic mechanism remain unclear." (PMID 36499275, 2022). "However, the role of FKBP1A in glioblastoma and the underlying biologic mechanism remain unclear." (PMID 36499275, 2022).
breast tumors (3 papers, 2010 to 2022). "Previous research showed that FKBP1A silencing in breast tumor cells weakened doxorubicin-induced cytotoxicity." (PMID 36499275, 2022).
esophageal cancer (3 papers, 2022 to 2024). A primary or metastatic malignant neoplasm involving the esophagus. "We also tested the specificity of the FKBP1A gene by comparing mRNA levels with other cancer-related digestive systems, including pancreatic cancer (N = 8), esophageal cancer (N = 5), stomach cancer (N = 5), colon cancer (N = 5), and liver cancer (N = 5)." (PMID 38570626, 2024).
head and neck squamous cell carcinoma (3 papers, 2022 to 2024). A squamous cell carcinoma that arises from any of the following anatomic sites: lip and oral cavity, nasal cavity, paranasal sinuses, pharynx, larynx, and salivary glands. "Another study showed that FKBP1A was overexpressed in head and neck squamous cell carcinoma (HNSCC) and FKBP1A upregulation was strongly associated with lymph node metastasis and poor prognosis." (PMID 36361587, 2022).
liver cancer (3 papers, 2022 to 2024). An epithelial or non-epithelial malignant neoplasm that arises from the liver. "A subsequent multivariate survival analysis identified five key prognostic ARGs (ATIC, BAX, BIRC5, CAPNS1, and FKBP1A) that were used to construct prognostic risk models, which provided an accurate prognosis for patients with malignant liver tumors." (PMID 35402224, 2022). "In pancreatic cancer, the results revealed a significant increase of FKBP1A mRNA expression (p = 0.0073), while in other cancers, except liver cancer (p = 0.0022), the mRNA level was unchanged." (PMID 38570626, 2024). "The CPTAC database was used to analyze the expression of the FKBP1A protein in patients with liver cancer." (PMID 35402224, 2022). "The results revealed that the expression of FKBP1A mRNA from liver cancer increased in three data sets compared to the normal tissues." (PMID 36361587, 2022). "Using TCGA and ICGC databases, we screened 5 differentially expressed ARGs, including FKBP1A, and established prognostic models of liver cancer." (PMID 35402224, 2022). "The results from TCGA database indicated that overexpression of ATIC, BIRC5, BAX, CAPNS1, and FKBP1A was closely related to an inferior OS of patients with liver cancer." (PMID 35402224, 2022). "In vitro cell function assays confirmed that FKBP1A knockdown significantly altered the biological behavior of liver cancer cells and that its downregulation decreased cell proliferation, migration, and invasion." (PMID 35402224, 2022). "Moreover, our experiments revealed that the tumor specific property that elevated FKBP1A gene expression was not only found in pancreatic cancer WBCs but also in hepatic cancer." (PMID 38570626, 2024). "To enhance the understanding of the correlation for the potential mechanism of FKBP1A gene expression in liver cancer, we further analyzed the correlation between FKBP1A expression and various clinical characteristics in LIHC patients using the Kaplan–Meier plotter." (PMID 36361587, 2022). "FKBP1A was expressed at higher levels in liver cancer than that in normal liver tissues." (PMID 35402224, 2022).
ovarian carcinoma (3 papers, 2021 to 2023). A malignant neoplasm originating from the surface ovarian epithelium. "This probe is located on chromosome 20 and mapped to two nearby genes: FKBP1A-SDCBP2, with an unclear functional role in humans, and SDCBP2-AS1, which has been linked to ovarian cancer." (PMID 37992405, 2023).
glioma (2 papers, 2011 to 2022). A benign or malignant brain and spinal cord tumor that arises from glial cells (astrocytes, oligodendrocytes, ependymal cells). "FKBP1A is essential for the effective and durable inhibition of mTORC1 and proliferation in human glioma cells by RapaLink-1, a third-generation mTOR kinase inhibitor." (PMID 36499275, 2022). "In particular, a third-generation mTOR inhibitor, RapaLink-1, which inhibits mTORC1 and proliferation in human glioma cells, requires FKBP1A in order to be practical and durable." (PMID 36499275, 2022).
invasive breast carcinoma (2 papers, 2019 to 2020). A carcinoma that infiltrates the breast parenchyma. "One study on Eph receptors and invasive breast carcinoma suggested that the level of FKBP1A was significantly affected by EphB6, which was a target mRNA of miR-100, the changes in miRNAs and the target mRNA may have a role in PI3K/Akt/mTOR pathways." (PMID 32497068, 2020).
lung adenocarcinoma (2 papers, 2016 to 2022). A carcinoma that arises from the lung and is characterized by the presence of malignant glandular epithelial cells. "In addition, FKBP1A expression was significantly lower in COAD (colon adenocarcinoma), KICH (kidney chromophobe), LUAD (lung adenocarcinoma), THCA (thyroid carcinoma) (p < 0.05)." (PMID 36361587, 2022).
lymph node metastasis (2 papers, 2022 to 2024). "Focusing on the relationship between FKBP1A expression level and the clinical characteristics of patients with LIHC, we examined possible subgroup associations with FKBP1A expression based on tumor stage, grade, and lymph node metastasis through the UALCAN database." (PMID 36361587, 2022).
nephrotic syndrome (2 papers, 2025). A collection of symptoms that include severe edema, proteinuria, and hypoalbuminemia; it is indicative of renal dysfunction. "For instance, differentially expressed proteins such as rpmF, SAMDC1, FKBP1A, and rpsK were claimed to differentiate between steroid-sensitive nephrotic syndrome and steroid-resistant nephrotic syndrome." (PMID 40141093, 2025).
acute myeloid leukemia (1 paper, 2023). Acute myeloid leukemia (AML) is a group of neoplasms arising from precursor cells committed to the myeloid cell-line differentiation. "Several previously published studies suggested small molecule inhibitors that interact with the Peptidyl-prolyl cis-trans isomerase FKBP1A (FKB1A) protein and suppress cell proliferation in acute myeloid leukemia phenotypes via inhibition of MTORC1 activity." (PMID 38138609, 2023).
atrial fibrillation (1 paper, 2024). A disorder characterized by an electrocardiographic finding of a supraventricular arrhythmia characterized by the replacement of consistent P waves by rapid oscillations or fibrillatory waves that vary in size, shape and timing and are accompanied by an irregular ventricular response. "Paroxysmal atrial fibrillation (AF) was also documented in mice with cardiomyocyte-specific FKBP1A overexpression." (PMID 39355352, 2024).
Ewing sarcoma (1 paper, 2012). A small round cell tumor that lacks morphologic, immunohistochemical, and electron microscopic evidence of neuroectodermal differentiation. "EPHA2 (encoding EphA2, ephrin type A receptor 2), VEGFC (vascular endothelial growth factor-C), and FKBP1A (FK506 binding protein 1A) were overexpressed in Ewing’s sarcomas." (PMID 23227212, 2012).
Immunodeficiency (1 paper, 2022). Failure of the immune system to protect the body adequately from infection, due to the absence or insufficiency of some component process or substance. "Combined together, it ascertains that LIHC FKBP1A upregulation stays tightly association with the immunodeficiency pathway in LIHC patients but not in the LIHC patients infected with the hepatitis virus or consumers of alcohol." (PMID 36361587, 2022).
kidney tumor (1 paper, 2021). "Specifically, we found that FKBP1A, 5–11, and 15 were upregulated in kidney tumor tissues, whereas others were downregulated." (PMID 34476212, 2021).
leukopenia (1 paper, 2018). "Individually, analysis of secondary outcomes revealed that FKBP2 c.-2110GG genotype carriers had higher risk of leukopenia, FKBP1A n.259+24936C allele carriers had increased risk of constipation, and FOXP3 c.-22-902A or c.-23+2882A allele had higher risk of gastrointestinal disorders (p < 0.05)." (PMID 30487748, 2018).
meningioma (1 paper, 2007). A generally slow growing tumor attached to the dura mater. "In line with the microarray data, the PCR data showed a decrease in the median expression level of BMP4, SMAD9, JUN, RUNX2 and an increase in the median expression level of FKBP1A in Grade 3 meningiomas when compared to Grade 1 meningiomas." (PMID 17937814, 2007).